CRP (C-reactive protein)
Diseases named in the same sentence as CRP in open-access papers (continued):
Sharing a sentence is not in itself a finding about the gene and the disease.
benign tumors (17 papers, 2014 to 2025). "The larger difference in cfDNA concentration between patients with malignant and benign tumors, than in CRP and LDH, clearly indicated the superior diagnostic potential of cfDNA to the conventional blood-circulating biomarkers." (PMID 33264292, 2020). "The benign tumor-patients group exhibited a CRP concentration and range of 4.5 (1.2–14) mg/L, CA125 concentration and range of 21.9 (3.4–122) U/ml, and HE4 of 75.5 (1.5–442) pmol/L." (PMID 33208875, 2020). "Previous studies have indicated that LD has antiinflammation effect and that the inflammatory response participates in I/R-induced cardiac injury; thus the effects of LD on inflammatory cytokines (IL-6, TNF-α and CRP) were also detected in the ischemic heart." (PMID 26058040, 2015). "Proinflammatory markers including serum C-reactive protein, IL-6, and IL-8 have all been used in clinical studies in an attempt to differentiate between normal, benign tumor, and OC." (PMID 25403235, 2014). "Regarding CRP inflammatory tests, canine-CRP (c-CRP) was in the normal range in healthy dogs; however, it was significantly higher in dogs with tumors compared with healthy dogs (p < 0.05), which was also significantly different between dogs with malignant and benign tumors." (PMID 36359174, 2022). "In this study, the pro-CRP, CEA, and NSE in the serum of patients with malignant and benign tumors were detected and compared." (PMID 35572829, 2022).
gastrointestinal disease (14 papers, 2014 to 2026). A disease that occurs in the gastrointestinal system, excluding the hepatobiliary system. "Various factors can influence the iron status in children, such as socioeconomic status, demography, the type of milk consumed by infants, dietary intake, elevated inflammation levels (e.g., C-reactive protein) and gastrointestinal diseases." (PMID 35745183, 2022). "These materials are especially relevant in addressing challenges in gastrointestinal disease diagnostics, where the sensitive and specific detection of biomarkers like C-reactive protein, fecal calprotectin, or mucosal antibodies is critical for early and accurate disease detection." (PMID 40277704, 2025). "Considering that a combination of different parameters (weight, height, nutritional need, malabsorption due to gastrointestinal disease and CRP) contribute to the GLIM score, the score could not be calculated if one of these parameters was not available." (PMID 38280135, 2024).
gastrointestinal disorders (14 papers, 2014 to 2025). "In this study, the finding of a clinical value of SAA is in line with other studies in which SAA has shown more promise as a diagnostic marker than CRP for gastrointestinal disorders linked with inflammation." (PMID 25430894, 2014). "In dogs, C-reactive protein is commonly used to evaluate patients with gastrointestinal disorders such as chronic inflammatory bowel disease." (PMID 37762074, 2023). "Beyond DD, CRP has also shown prognostic value in patients with other gastrointestinal disorders." (PMID 41517338, 2025).
intestinal disease (13 papers, 2010 to 2025). "Serum amyloid A (SAA), haptoglobin, fibrinogen, and C-reactive protein (CRP) have all been explored as biomarkers to differentiate the cause of intestinal disease in the horse." (PMID 36670767, 2023). "One disadvantage of CRP as a biomarker is the low sensitivity for intestinal diseases due to its increase during any state of systemic inflammation." (PMID 38256249, 2024). "Further, as clinical symptoms poorly correlate with intestinal disease activity, this last one is evaluated by a set of laboratory indices (C-reactive protein (CRP), fecal calprotectin), endoscopy and imaging tests." (PMID 34575156, 2021). "Previously, the identified independent risk factors for poor prognosis in intestinal ABD were male gender, mucosal healing, volcano-shaped ulcers, larger size of intestinal ulcers (> 2 cm) and elevated CRP levels (≥ 44 mg/L )." (PMID 31779646, 2019). "As the eligibility criteria ensured the absence of symptoms reflecting acute or chronic diarrhea and most participants presented with low circulating CRP concentrations, we do not believe underlying intestinal disorders to have biased our results." (PMID 37037953, 2023). "Compared to other patients in two other groups (located in ileocecal alone or colorectum alone), these patients tended to be older, have more intestinal ulcers, lower Hb concentrations, and higher ESR or CRP levels, all of which are adverse items for poor outcomes in intestinal ABD." (PMID 31779646, 2019). "Furthermore, a study reported that the specificity for predicting intestinal ulcers was higher with dual positive LRG and faecal calprotectin than LRG alone, whereas the combination of LRG and CRP was not evaluated." (PMID 39823192, 2025).
musculoskeletal disease (11 papers, 2007 to 2026). "CRP levels in the group with poor recovery were similar to those reported for other painful musculoskeletal conditions including work related musculoskeletal disorders and acute sciatic pain." (PMID 24147095, 2013). "RCTs and clinical trials revealed, after BT, a reduction in circulating levels of pro-inflammatory molecules, such as TNF-α, IL-1β, and C-reactive protein, and an increase in anti-inflammatory molecules such as the IGF-1 growth factor especially in musculoskeletal diseases." (PMID 34035862, 2021). "The balance between the risks and benefits of these competing views of the role of CRP in disease and disease therapy is reminiscent of the ongoing controversy regarding the use of non-steroidal anti-inflammatory drugs (NSAIDs) for musculoskeletal disease and their cardiovascular side effects." (PMID 19690638, 2007).
myopathy (11 papers, 2012 to 2025). A disease of the muscle in which the muscle fibers do not function properly. "In our study, we observed a strong correlation between higher levels of serum resistin and CRP and, most importantly, we observed an association with the global disease activity assessment of inflammatory myopathy." (PMID 22577940, 2012). "Increased levels of C-reactive protein were probably due to the systemic inflammation of anti-SRP myopathy." (PMID 25963141, 2015). "After the exclusion of infectious causes (normal white blood count, negative C-reactive protein, negative viral panel) and other secondary causes (toxic substances, medication, endocrinopathy, or systemic disease), an idiopathic inflammatory myopathy was considered the most probable diagnosis." (PMID 39355458, 2024). "Her erythrocyte sedimentation rate (ESR) and C-reactive protein (CRP) were minimally elevated, ruling out inflammatory myopathy." (PMID 39759753, 2024). "However, aside from directly accessing the myocytes, this virus can induce myopathy, muscle weakness and atrophy indirectly by upregulating proinflammatory cytokines, such as interleukin 1 beta (IL-1β) and 6 (IL-6), C-reactive protein (CRP), and tumor necrosis factor (TNF)." (PMID 34248502, 2021). "In patients with inflammatory myopathies, but not in healthy controls, the serum resistin levels correlated with the CRP levels (r = 0.328, P = 0.040) and, interestingly, positively correlated with the global MYOACT score (r = 0.382, P = 0.026)." (PMID 22577940, 2012).
electrolyte imbalance (9 papers, 2020 to 2025). "Results showed that seven parameters, the NLR, PLR, IL‐6, CRP, CT score, patients who need nutrition support, and electrolyte imbalance, were positively correlated with the risk of critical patients." (PMID 32860454, 2020). "CRP levels were also significantly higher in obese patients with electrolyte imbalance (60 ± 16 mg/L vs. 50 ± 13 mg/L, p < 0.001), with a strong correlation between CRP and imbalance severity (R2 = 0.48, p < 0.001)." (PMID 40002762, 2025).
blood tumor (8 papers, 2020 to 2025). "Nevertheless, some non-specific diagnostic markers, such as complete blood count (CBC), erythrocyte sedimentation rate (ESR), and C-reactive protein (CRP), are commonly employed in clinical practice to monitor the growth and progression of hematological neoplasms." (PMID 37987280, 2023).
hematological cancers (7 papers, 2017 to 2025). "For late mortality, a model incorporating age, wave number, hematologic cancer, C-reactive protein, lactate dehydrogenase, and platelet counts resulted in an AUC of 0.795 (p < 0.001; 95% CI, 0.759-0.831)." (PMID 39538084, 2024). "First, among blood and biochemical measurements, the hematologic cancer cohort displayed increased CRP and D-dimer concentrations and lower hematocrit and hemoglobin levels in patients that progressed to death (Severe-Death group)." (PMID 36700209, 2022). "While CXCL8 and IL-6 were the most important factors that segregated Severe-Death solid tumors patients, CXCL8, CRP and IL-6 had important roles for segregation of patients with hematologic cancers." (PMID 36700209, 2022). "In the present study, we also evaluated the correlation between the BNP and CRP levels in the patients with hematological cancers and solid tumors." (PMID 28570595, 2017). "Conversely, biochemical analysis showed augmented levels of CRP and D-dimer in the Severe-Death hematologic cancer patients as compared to the Mild group, whereas none of the hematological or biochemical parameters differed between solid tumor patients with distinct clinical outcomes." (PMID 36700209, 2022). "There was a significant positive relationship between the BNP and CRP levels in the patients with solid tumors, but not hematological cancers." (PMID 28570595, 2017).
endocrine disease (6 papers, 2013 to 2024). "Data concerning the impact of probiotics on CRP levels of patients or animals with endocrine disorders were extracted from five articles." (PMID 38504163, 2024). "A notable improvement was seen following 4 months of therapy, as evidenced by normalization of CRP, hemoglobin, albumin, renal function, and resolution of his endocrinopathy." (PMID 31453020, 2019).
brain disorder (3 papers, 2005 to 2023). A disease affecting the brain or part of the brain. "The only two significant increases in knowledge are on questions concerning C-reactive protein (a relatively recently introduced clinical test), and on the diagnosis of organic brain disease." (PMID 16026607, 2005).
head and neck tumors (3 papers, 2024 to 2025). "Particularly in the group of head and neck tumors, parameters were identified that showed an association with PFS: Leukocyte, neutrophil, and CRP-albumin ratio values above the median were associated with shorter PFS." (PMID 41361351, 2025).
neoplastic disorders (3 papers, 2023 to 2025). "Almost all infectious, autoimmune, ischemic, and neoplastic disorders can lead to a rise in blood CRP levels." (PMID 39727640, 2024). "Against this background, in this study, we aimed to investigate associations between lymphadenomegaly and levels of the inflammatory markers, primarily CRP, using CT images of deep lymph nodes (sternal, cranial mediastinal, and iliac lymph nodes) in small dogs with non-neoplastic disorders." (PMID 40284858, 2025).
digestive system cancer (2 papers, 2013 to 2024). A primary or metastatic malignant neoplasm involving any part of the digestive system. "Furthermore, elevated levels of CRP have also been described as a prognostic factor in various types of human malignancy, including digestive system cancers." (PMID 24255664, 2013).
animal diseases (1 paper, 2021). "Serum protein profiles and C-reactive protein (CRP) levels are used widely to diagnose several animal diseases." (PMID 34083932, 2021).
diseases of the reproductive (1 paper, 2020). "CRP analyses of patients with diseases of the reproductive organs are likely underrepresented in our study as they are primarily referred to the clinic for obstetrics." (PMID 32434519, 2020).
urinary tract disorders (1 paper, 2022). "Ultrasonography (USG), magnetic resonance imaging (MRI), complete blood count (CBC), inflammatory markers (C-reactive protein—CRP), renal function tests, urinary analysis, and urine culture are useful diagnostic tools for detection of urinary tract disorders during pregnancy." (PMID 35630036, 2022).
CRP also shares sentences with these, for which no sentence is quoted: acute myocardial infarction (191 papers); chronic periodontitis (46); polymyalgia rheumatica (30); acute respiratory failure (26); viral disease (22); magnesium deficiency (17); Sleep disturbance (14); thrombophilia (14); cardiac arrhythmia (13); acute myocarditis (12); joint effusion (11); portal hypertension (11); non-Hodgkin lymphoma (10); idiopathic pulmonary fibrosis (9); diarrhoea (8); granulocytosis (7); hyperlipemia (7); movement disorder (7); nasal obstruction (7); Takotsubo cardiomyopathy (7); cardiac tamponade (6); dialysis (6); Ovarian cyst (6); Parkinson’s (6); allergic rhinitis (5); autoimmune encephalitis (5); Chorea (5); cranial nerve palsy (5); Hearing impairment (5); hemochromatosis (5).
A further 546 diseases each share a sentence with CRP in 5 papers or fewer.